TRPM8 (transient receptor potential cation channel subfamily M member 8)
Diseases named in the same sentence as TRPM8 in open-access papers (continued):
Sharing a sentence is not in itself a finding about the gene and the disease.
cancer (119 papers, 2008 to 2025). A tumor composed of atypical neoplastic, often pleomorphic cells that invade other tissues. "TRPM8 is expressed in several tissues, including the breast, pancreas, bone and colon, and its overexpression has been associated with cancer hallmarks such as cell migration and invasion." (PMID 40813985, 2025). "Various diseases, such as chronic cough, cancer, migraines, and irritable bowel syndrome, have been linked to TRPM8 pathology." (PMID 38680092, 2024). "So far several reports have suggested that changes in the expression of TRPM8 can be linked with the development as well as progression of cancer stages." (PMID 39150496, 2024). "The frequency of the cancer mutation observed in the LWI region is ~ 61% (for 60 amino acids) and the frequency of the cancer mutation observed in the rest of the TRPM8 regions is 39% (1104–60 = 1044 amino acids)." (PMID 39150496, 2024). "This strongly suggests the importance of TRPM8 in cancer and also suggests somatic mutations in TRPM8 at the LWI region as a possible causal factor for cancer progression (discussed later)." (PMID 39150496, 2024). "Consistent with its unique deregulation during PCa progression, alterations in TRPM8 channel activity have been linked to several cancer hallmarks, including tumor cell proliferation and survival, cell migration, and angiogenesis." (PMID 37576340, 2023). "TRPM8 channels in cancer prognosis are associated with the modulation of cell viability, proliferation, migration, and apoptosis." (PMID 37892239, 2023). "Ion channel activity and associated signaling pathways are highly regulated in cancer, and TRPM8 has been proposed as a molecular target in cancer development and progression." (PMID 37033630, 2023). "TRPM8 channels have also been associated with different types of cancer, where they seem to contribute to cellular proliferation and migration." (PMID 35976012, 2022). "We found that TRP family genes are extensively involved in tumour progression and serve as risk factors for most tumours— especially TRPM2, TRPM4, and TRPM8 leading to poor prognosis of patients with cancer." (PMID 35493463, 2022). "For example, the expressions of TRPM2, TRPA1, and TRPM8 were associated with patient survival in 22, 16, and 19 cancer types, respectively." (PMID 35614079, 2022). "TRPM8 was found to modulate genes involved in DNA repair and methyltransferase activity, as well as regulate cancer-associated signaling pathways." (PMID 35847920, 2022). "More importantly, sometimes the TRPM8 overexpression was associated to poor prognosis of cancer patients." (PMID 32843690, 2020). "Little is known about the mechanism underlying the up-regulated expression of TRPM8 in the other malignant tumors." (PMID 26512697, 2015). "Recent data have begun to reveal the signaling mechanisms underlying the TRPM8 channels-mediated biological effects of cancer." (PMID 26512697, 2015). "TRPM8-mediated currents and the associated increase in [Ca2+]ic have been demonstrated in various types of cancer cells." (PMID 26512697, 2015). "Several in vivo studies have implicated the contributory roles of TRPM8 in cancer growth and metastasis." (PMID 26512697, 2015). "This pattern of variation in TRPM8 channel expression makes it an interesting candidate as a diagnostic marker for detection of cancer and as prognosis marker for evaluating the outcome of epithelial cancers." (PMID 24204345, 2013). "Furthermore, given the reported associations of ZNF334, Hsp90 and TRPM8 with tumor progressions, and the potential of cancer hyperthermia therapies, this study also provides hints in thermal modulation of tumor stress responses." (PMID 41168503, 2025). "Since the upregulation of TRPM8 channels has been linked to various autophagy-related cancers, suggesting that targeting the regulation of autophagy through TRPM8 channels could be a potential therapeutic strategy." (PMID 40078961, 2025).
cancer (continued). "It is also important to note that cancer patients seem to have diverse somatic mutations in TRPM8." (PMID 39150496, 2024). "The effects of TRPM8 channels in cancer prognosis are associated with modulation of cell viability, proliferation, migration, and apoptosis; phenomena demonstrated employing TRPM8 overexpression, knockdown, and channel regulation activity by agonist or antagonist." (PMID 37033630, 2023). "TRPM8 was linked to the effect of other chemotherapeutics, including Lapatinib, Erlotinib, Afatinib, and Dabrafenib, which are approved for treating diverse cancers." (PMID 37033630, 2023). "TRPM8 was also linked to unfavorable patient outcomes and cancer-associated signaling." (PMID 35847920, 2022). "Since upregulation of TRPM8 channel is implicated in several autophagy-related cancers, the regulation of basal autophagy by TRPM8 channel may be a possible therapeutic target." (PMID 33344232, 2020). "Finally, TRPA1 has been also related in thermal and mechanical allodynia caused by many neurotoxic cancer chemotherapies together with TRPM8 and TRPV1." (PMID 25257900, 2014). "Furthermore, several in vivo studies have linked TRPM8 to cancer growth and metastasis." (PMID 27289382, 2016). "Previous studies on different types of cancer, including lung, breast, and prostate carcinoma, have also shown that TRPM8 is expressed at higher levels in tumor tissues than in normal tissues." (PMID 40869148, 2025). "In conclusion, our findings indicate that α‐acyloxy carboxamide 23 is a potential therapeutic TRPM8 antagonist that attenuates pathological cold allodynia arising from a common peripheral neuropathy in cancer patients." (PMID 40123199, 2025). "This study underscores the importance of TRPM8 as a potential therapeutic target and biomarker in PC, warranting further investigation into its role in cancer biology and treatment response." (PMID 40214455, 2025). "We suggest that mutations and/or physiological conditions can potentially alter these TRPM8-cholesterol complexes and can lead to physiological disorders or even apparently irreversible diseases such as cancer and neurodegeneration." (PMID 39150496, 2024). "Investigations focusing on TRPM8 in esophageal, gastric, intestinal, hepatic, and pancreatic disorders mainly revolve around inflammation, cancer, sensory responses, and motility." (PMID 39062591, 2024). "Taken together, the data strongly suggest that TRPM8 cholesterol crosstalk is important for cellular functions and alteration of such crosstalk can be relevant in different cancer conditions." (PMID 39150496, 2024). "Recent studies in our laboratory have revealed that TRPM8 is upregulated in various cancers with high levels of autophagy." (PMID 39633507, 2024). "In the realm of pancreatic research, cancer has emerged as a prime focus of TRPM8-related investigations." (PMID 39062591, 2024). "TRPM8 plays a crucial role in various physiological and pathological processes such as esophageal sensation, motility, inflammation, and cancer." (PMID 39062591, 2024). "In previous studies, menthol has reported as anti-cancer agents in several cancer types via the transient receptor potential melastatin 8 (TRPM8)-dependent pathway or in TRPM8-independent manner." (PMID 36923503, 2023). "TRPM8 has been proposed as a therapeutic target for cancer treatment because of its demonstrated role in cancer development and progression." (PMID 37033630, 2023). "Taken together, initial studies have demonstrated that TRPM8 channels have several functions in cancer, including roles in cell proliferation, cell survival, and metastasis." (PMID 37445615, 2023). "In this review, we summarize the current knowledge on the role of TRPM8 channels in cancer progression." (PMID 37033630, 2023). "TRPM8 agonists modulate various properties in cancer cells, and menthol is one of the most extensively used pharmacological studies." (PMID 37033630, 2023).
cancer (continued). "Since TRPM8 is also expressed in a broad range of adenocarcinomas (such as breast and stomach), TRPM8-positivity lacks specificity for determining the primary site of the cancer." (PMID 37240443, 2023). "This review aims to describe the role of the TRPM8 channel in carcinogenesis and the therapeutic potential of this channel in cancer treatment." (PMID 37033630, 2023). "Transcripts of AMACR, GOLM1, TRPM8 and NKX3-1 genes were overexpressed and were closely associated with cancer aggressiveness, extracapsular extension and vesicular seminal invasion." (PMID 37091783, 2023). "Combination therapy uses two or more therapeutic agents for cancer treatment, and there are exciting reports about the potential use of TRPM8 modulators combined with currently used chemotherapeutics." (PMID 37033630, 2023). "TRPM8 channel activity is also involved in cancer development and progression, and channel overexpression is regularly associated with poor prognosis." (PMID 37033630, 2023). "Different reports demonstrate the role of TRPM8 channels in cancer through the modulation of channel expression or activity." (PMID 37033630, 2023). "In principle, TRPM8-positive cancer cells can be found and visualized in the body by radiohalogen ligands." (PMID 37240443, 2023). "We also discuss the therapeutic potential of TRPM8 in carcinogenesis, which has been proposed as a molecular target for cancer therapy." (PMID 37033630, 2023). "More profound studies are necessary, focusing on the relationship between the TRPM8 channel and the activity of chemotherapeutics currently used in cancer treatment to get an improved therapy using FDA-approved drugs." (PMID 37033630, 2023). "TRPM8 knockdown decreases basal autophagy, while TRPM8 overexpression increases basal autophagy in several mammalian cancer cell types." (PMID 37892239, 2023). "TRPM8 activation was augmented by menthol, whereas the small molecule TRPM8 antagonist RQ-00203078 blocked the migration of cancer cells in gelatin." (PMID 37240443, 2023). "This bodes well for the potential use of TRPM8, or of the peptide sequence involved in the functional interaction with Rap1 alone, in cancer therapy to prevent and/or block its metastatic degeneration." (PMID 35565390, 2022). "A recent bioinformatic analysis showed that TRPM8 modulates immune infiltration and influences patient outcomes in many cancers, including PDAC." (PMID 36012311, 2022). "First, TRPM8 expression varies during cancer progression, with strong expression in the initial PCa stages and loss of expression in the late and more aggressive stages." (PMID 35743115, 2022). "We found a higher metastatic rate in mice grafts with PC3 luc compared with those grafted with TRPM8–overexpressing PC3–M8 luc cancer cells." (PMID 35743115, 2022). "In agreement, picomolar concentrations of dihydrotestosterone induced pronounced overexpression of TRPM8 in cancer cells whereas higher concentrations had a reduced effect." (PMID 36272975, 2022). "Then, differential expression analysis was separately performed on RAP1A and TRPM8 transcript levels in each one of the three cancer cohorts." (PMID 35565390, 2022). "The integration of the GTEx and TCGA data in 33 cancers indicates an elevation of TRPM8 levels in most solid tumors." (PMID 35847920, 2022). "The abnormal increase of TRPM8 mRNA expression in some cancers is likely a result of lower DNA methylation levels." (PMID 35847920, 2022). "While TRPM8 antagonists are reported as potential drugs for pain, cancer, and inflammation, to date only a limited number of chemotypes have been investigated and thus a limited number of compounds have reached clinical trials." (PMID 35216186, 2022).
cancer (continued). "In these studies, the expression levels of TRPV4, TRPM2, TRPM4, and TRPM8 in cancer tissues are significantly increased, which is consistent with our OV research." (PMID 35813831, 2022). "Altogether these findings provide new insights into potential therapeutic approaches involving TRPM8 as a target for cancer progression treatments." (PMID 35565390, 2022). "Menthol, in bladder cancer cell line (T24) induced mitochondrial membrane depolarization via increasing the Ca2+ level through the overexpression of TRPM8 in T24 cells leading to cancer cell death." (PMID 35267408, 2022). "It has been reported that cancer induces the efflux of Ca2+ from bones into the bloodstream, hence activating a calcium-permeable channel (TRPM8) resulting in cell death." (PMID 35267408, 2022). "Validation of these residues on different cancer cell lines suggests a broad spectrum of action of this Ca2+-independent TRPM8-Rap1A interplay in terms of control of cell adhesion and migration." (PMID 35565390, 2022). "For example, TRPM8 is a calcium permeability channel abnormally expressed in multiple malignant tumors." (PMID 36105089, 2022). "This study deepens our knowledge of the mechanism through which TRPM8 would exert a protective role in cancer progression and provides new insights into the possible use of TRPM8 as a new therapeutic target in cancer treatment." (PMID 35565390, 2022). "The Pan-Cancer analysis suggests the potential of TRPM8 as a treatment target or biomarker for determining the prognosis of a specific type of cancer." (PMID 35847920, 2022). "Some Ca2+-permeable channels have been implicated in the enhanced migration of various cancers: TRPC1, TRPM7, TRPM8, TRPV1, TRPV2, TRPV6, STIM1, Ca2+-release activated Ca2+ modulator 1 (Orai1) and some types of VGCCs." (PMID 36046118, 2021). "Despite the number of studies focused on understanding the TRPM8 connection to cancer, forthcoming treatments with TRPM8 modulators are still in need of more coordinated investigations." (PMID 34445208, 2021). "As specified in the previous section, and backed up by an incessant flow of published articles, TRPM8 channel expression is ligated to the progression, migration, and invasion of tumor cells in different cancer malignancies." (PMID 34445208, 2021). "In this study, overexpression of TRPM8 enhanced the level of basal autophagy, whereas TRPM8 knockdown reduced the level of basal autophagy in several types of mammalian cancer cells." (PMID 33344232, 2020). "Much attention has been given to the contribution of TRPM8 in cancer, and particularly prostatic cancer." (PMID 33147416, 2020). "Regarding TRPM8, experimental data have revealed that this channel modulates cell proliferation, survival, and invasion depending on the cancer cell type and AR requirements." (PMID 32344908, 2020). "Our findings indicate that TRPM8 is a universal master regulator of basal autophagy that maintains and regulates the level of basal autophagy in several types of mammalian cancer cells." (PMID 33344232, 2020). "This study demonstrated that TRPM8 as a positive regulator that promotes basal autophagy in several types of mammalian cancer cells." (PMID 33344232, 2020). "We therefore examined the mRNA expression of seven cannabimimetic receptors – CNR1 (CB1), CNR2 (CB2), GPR55, TRPV1, TRPV2, TRPA1, TRPM8 – and found them to be differentially expressed amongst the 12 tested cancer cell lines." (PMID 31289609, 2019). "Regarding agonists or antagonists of TRPM8 channels, several are now considered in cancer prevention and therapy, although some of those reported in the literature lack selectivity for TRPM8 because they also act on TRPV1 and TRPA1." (PMID 31801263, 2019). "It is particularly interesting that TRPM8 expression pattern differed between the normal prostate and the cancer cells." (PMID 28039451, 2017).
cancer (continued). "The rescuing of functional TRPM8 channels, in turn, negatively impacted cancer cells growth and proliferation and induced apoptosis, which was evidenced by TUNEL staining and transmission electron microscopy." (PMID 28039451, 2017). "Experimental data demonstrated that TRPM8 channels play important roles in general in cancer cells, in particular in their proliferation, survival, migration, invasion and neurosecretion." (PMID 27289382, 2016). "Among them, the intracellularly located channels that are related to cancer development and progression identified so far are TRPM8 and TRPC1." (PMID 27289382, 2016). "In order to make sense of TRPM8’s role in prostate carcinogenesis, the different hallmarks of cancer should be studied separately; at the beginning, by taking into account the androgen dependency of the PCa cells in the various stages of advancement." (PMID 27409624, 2016). "These processes have been defined as being hallmarks of cancer and TRPM8 plays a role in all of these." (PMID 27409624, 2016). "In particular, TCAF-1 is more expressed in the early tumor stages favoring cancer development, while its expression as well as that of TRPM8 is reduced during the tumor spreading with metastasis." (PMID 27289382, 2016). "Firstly, it has been demonstrated that expression of TRPM8 varies during cancer progression and the androgen-dependence of TRPM8 expression has been demonstrated." (PMID 27409624, 2016). "Further, TRPM8-mediated cancer cell migration has been seen to be regulated by the newly identified partner proteins of the channel." (PMID 27409624, 2016). "Accumulating evidence implicates that TRPM8 is involved in diverse human disorders, particularly cancer." (PMID 26512697, 2015). "Experimental data implicate that TRPM8 channels play important roles in cancer cells proliferation, survival, migration, invasion, and neurosecretion." (PMID 26512697, 2015). "Determining the mechanistic roles of TRPM8 in cancer is expected to elucidate the impact of thermal and chemical stimuli on the formation and progression of neoplasms." (PMID 26512697, 2015). "Experimental data have revealed important roles of TRPM8 channels in cancer cells proliferation, survival, and invasion, which appear to be dependent on the cancer type." (PMID 26512697, 2015). "Results of the studies thus far show that TRPM8 can have opposing effects on cancer cells proliferation, survival, and invasion." (PMID 26512697, 2015). "Recent studies have begun to reveal the mechanisms that mediate the various roles of TRPM8 channels in cancer cells proliferation, survival, migration, and invasion." (PMID 26512697, 2015). "It will be interesting to understand how the cancer cell types as well as the molecular phenotypes influence the roles of TRPM8 in proliferation." (PMID 26512697, 2015). "Research efforts to determine the mechanistic roles of TRPM8 in cancer are expected to shed new light on how the physical and chemical alterations in the environment impact on carcinogenesis." (PMID 26512697, 2015). "The results thus far indicate that TRPM8 plays an important role in regulating the proliferative capability of the cancer cells." (PMID 26512697, 2015). "Increasing data are expected to reveal the signaling mechanisms that mediate the various roles of TRPM8 channels in cancer cells proliferation, survival, migration, and invasion." (PMID 26512697, 2015). "On the other hand, over-expression of TRPM8 produces anti-proliferative effect in certain type of cancer cells." (PMID 26512697, 2015). "Emerging studies have demonstrated that TRPM8 channels are involved in cellular proliferation, survival, and invasion—some of the hallmarks of cancer." (PMID 26512697, 2015). "Tentatively, the signaling pathways downstream of TRPM8 channels are likely dependent on the cancer cells type and their genetic milieu." (PMID 26512697, 2015). "While normal expression is tissue-selective, TRPM8 is aberrantly expressed in a variety of malignant tumors." (PMID 26512697, 2015).